ENSG00000238390
Synonyms: LOC124900469
Gene: Small nucleolar RNA gene on chromosome 21 (31,664,306 to 31,664,482, forward strand). Ensembl gene ENSG00000238390.
Gene Ontology:
Biological process: RNA processing
Cellular component: nucleolus
Homologues: Paralogues in human: SNORA81 (86% identical).